IGHV3-15 (immunoglobulin heavy variable 3-15)
Description:
V region of the variable domain of immunoglobulin heavy chains that participates in the antigen recognition. Immunoglobulins, also known as antibodies, are membrane-bound or secreted glycoproteins produced by B lymphocytes. In the recognition phase of humoral immunity, the membrane-bound immunoglobulins serve as receptors which, upon binding of a specific antigen, trigger the clonal expansion and differentiation of B lymphocytes into immunoglobulins-secreting plasma cells. Secreted immunoglobulins mediate the effector phase of humoral immunity, which results in the elimination of bound antigens. The antigen binding site is formed by the variable domain of one heavy chain, together with that of its associated light chain. Thus, each immunoglobulin has two antigen binding sites with remarkable affinity for a particular antigen. The variable domains are assembled by a process called V-(D)-J rearrangement and can then be subjected to somatic hypermutations which, after exposure to antigen and selection, allow affinity maturation for a particular antigen.
Synonyms: IGHV315; VH
Gene: Immunoglobulin variable (V) gene on chromosome 14 (106,153,624 to 106,154,163, reverse strand). Ensembl gene ENSG00000211943.
Subcellular location: Secreted; Cell membrane
Gene Ontology:
Molecular function: antigen binding
Biological process: immunoglobulin mediated immune response
Cellular component: extracellular region; plasma membrane
Homologues: Orthologues: macaque IGHV3-15 (76% identical), mouse Ighv7-3 (67% identical), mouse Ighv7-4 (65% identical), mouse Ighv7-1 (63% identical), mouse Ighv7-2 (61% identical). Paralogues in human: IGHV3-49 (84% identical), IGHV3-73 (84% identical), IGHV3-72 (82% identical), IGHV3-23 (82% identical), IGHV3-74 (80% identical), IGHV3OR15-7 (80% identical), IGHV3-35 (78% identical), IGHV3-43 (78% identical), IGHV3-66 (78% identical), IGHV3OR16-13 (78% identical), IGHV3-53 (77% identical), IGHV3-11 (76% identical), and 65 more.